CCR8 (C-C motif chemokine receptor 8)
Diseases named in the same sentence as CCR8 in open-access papers (continued):
Sharing a sentence is not in itself a finding about the gene and the disease.
tumor (continued). "CCR4 and CCR8 have recently been identified as being more selectively expressed on tumor-reactive eTregs." (PMID 39227959, 2024). "In solid tumours, CCL1 is produced by TME‐composed cells such as TAMs, CAFs and regulatory T cells (Treg), and acts through CCR8 expressed in tumour cells, vascular endothelial cells and Treg." (PMID 38506205, 2024). "The overall tumor assessment with the WTA protocol showed a weak positive correlation between CCR8+ Treg infiltration and GzmB expression in CD8+ T cells." (PMID 38783281, 2024). "This highlights the biological importance and clinical relevance of CCR8+ Tregs in anti-tumor immunity." (PMID 38783281, 2024). "They found that CCL1, secreted by activated T cells, provides positive feedback for the recruitment of CCR8 T cells to the tumor tissue, thereby increasing CAR-T cell infiltration and synergizing with DNR to mitigate tumor-derived immunosuppressive signals." (PMID 39350256, 2024). "Few M2b macrophages can be identified in early stage HCC; they increase in preponderance in parallel with increasing tumor stages, gradually overtaking the population of M1 cells, with M2b cells and the CCL1/CCR8 axis being linked." (PMID 39796695, 2024). "All of these results suggested that tumour-infiltrating CCR8+ Tregs were retained in the TME by CCL18+ macrophages." (PMID 37935468, 2024). "We investigated the association of CCR8+ Tregs and GzmB+ CD8+ T cells in tumor tissues and further evaluated the prognostic impact of their distribution profiles." (PMID 38783281, 2024). "The high level of CCR8 expression on freshly isolated TITRs suggests that CCR8 expression on TITRs is persistent and stable in the tumor microenvironment." (PMID 38231448, 2024). "The expression of CCR8, the receptor of CCL1, has also been found on tumor-associated macrophages (TAMs) as well as other myeloid cell subsets." (PMID 39409924, 2024). "TI-Tregs express a broad range of specific genes, including CCR8, which is a candidate therapeutic target playing a vital role in the recruitment of Tregs to sites of tumor and inflammation." (PMID 38509593, 2024). "Histological analysis revealed that the number of CCL1‐positive cells, mainly tumour associated macrophages (TAMs) located in the stroma of CRC, decreased significantly at liver metastatic sites, while the expression level of CCR8 on CRC remained unchanged." (PMID 38506205, 2024). "CCR8-expressing regulatory T cells (Tregs) are selectively localized within tumors and have gained attention as potent suppressors of anti-tumor immunity." (PMID 38783281, 2024). "In a mouse model of pancreatic solid tumors, CCR8-DNR-CAR-T cells targeting murine EpCAM achieved a tumor rejection rate in three out of seven mice." (PMID 39350256, 2024). "The human CC chemokine receptor 8 (CCR8) is specifically expressed on tumor-infiltrating regulatory T cells (TITRs) and is a promising drug target for cancer immunotherapy." (PMID 38231448, 2024). "A previous study showed that two CCL18 receptors, PITPNM3 and CCR8, were highly expressed in tumour-infiltrating Tregs." (PMID 37935468, 2024). "These CCR8-CAR-T cells are recruited to tumor sites via the CCL1-CCR8 axis, potentially enhancing the efficacy of CAR-T cell therapy." (PMID 39136031, 2024). "By analysing different single-cell sequencing data for CRC, we found that CCR8 was also specifically expressed in tumour-infiltrating Tregs in CRC." (PMID 37935468, 2024). "CCR8 upregulation was found in tumor-infiltrating Treg cells and correlated with poor prognosis in solid tumors, and targeting CCR8 for Treg depletion elicits antitumor immunity and synergizes with immunotherapy." (PMID 37770937, 2023). "Our study demonstrated that oxamate reduced the number of tumor-infiltrating Treg cells through inhibiting CCR8 expression, lactate increased CCR8 expression in cultured CD4 + T cells in vitro." (PMID 37770937, 2023).
tumor (continued). "Recent preclinical mouse experiments have demonstrated that depletion of mouse Treg cells using an anti-murine CCR8 antibody can result in strong anti-tumor responses." (PMID 38040762, 2023). "CCR8 is a chemokine receptor that has recently been identified as a potential specific marker for tumor-infiltrating Tregs and a core member of the interferon regulatory factor 4 (IRF4)-dependent “effector” Treg gene program." (PMID 37182149, 2023). "Upon Treg cell depletion, CCR8+ Tconv cells undergo systemic and intratumoral activation and expansion, and mediate IL-10 dependent suppression of anti-tumor immunity." (PMID 38100544, 2023). "A promising immunotherapeutic strategy for the treatment of breast cancer would involve targeting CCR8 to prevent the migration of tumor-resident Tregs." (PMID 37056346, 2023). "While CCR8 antibody treatment alone diminished tumor growth, a markedly more pronounced effect was observed when it was combined with VEGF blockade." (PMID 37127830, 2023). "As an important chemokine receptor on Tregs, the regulatory effect of CCR8 on tumor immunity has received more and more attention." (PMID 37950246, 2023). "CCR8 is expressed by skin resident memory T cells, which are thought to be the tumor cell of origin in mycosis fungoides." (PMID 36765704, 2023). "In comparison to CCR4, T cells expressing CCR8 are much less common, being primarily restricted to skin T cells and tumor Tregs." (PMID 37182149, 2023). "C-C chemokine receptor 8 (CCR8) is a chemokine receptor that is selectively expressed on tumor-infiltrating Tregs in NSCLS." (PMID 36776832, 2023). "It is also reported that CCR8 was upregulated in tumor-tissue Tregs and these CCR8+ Tregs have high activity and proliferation potential." (PMID 37835465, 2023). "Our analysis on immune cell subsets from separated tumor tissues showed high expressions of CCR8 on Treg cells in control T and CAR-T groups, oxamate treatment reduced CCR8 expressions, while elevated IL-17 A expressions in CD4 + T cells." (PMID 37770937, 2023). "When targeting CCR8 with specific antibodies in monotherapy, there was a significant reduction in tumor growth, similar to what has been observed with the use of anti-PD-1 blocking antibodies." (PMID 36765704, 2023). "Overall, high levels of CCL1 and CCL18 in OC tissues can recruit CD4+CCR8+ Tregs into tumor tissues by recognizing CCR8 on cells and remodeling their inhibitory phenotypes, making them have stronger immunosuppressive phenotypes and proliferative abilities." (PMID 37950246, 2023). "Researchers compared the RNA-seq data of Tregs in tumor tissues, normal tissues, and peripheral blood of breast cancer patients and found that Tregs at the tumor site had a high CCR8 expression." (PMID 37182149, 2023). "Increased expression of CCR8 was noticed in tumor infiltrating Tregs compared to circulating T regs." (PMID 37056346, 2023). "Patents are pending for CXCR6 transduced T cells for targeted tumor therapy, Improving adoptive cellular therapy, CCR8 transduced T cells for targeted tumor therapy and CSF1R-targeted immunotherapies." (PMID 37534876, 2023). "Recent reports revealed the selective expression of the chemokine receptor CCR8 on tumor Treg cells, making CCR8 a promising target in translational research." (PMID 35158783, 2022). "We performed RNA-sequencing of CCR8+ Tregs and CCR8− Tregs sorted from tumor-infiltrating cells (TICs) obtained from 3 patients and identified differentially expressed genes (DEGs) between CCR8+ Tregs and CCR8− Tregs." (PMID 35354899, 2022). "Chemokines (CXCL12, CXCL8, CXCL5) and chemokine receptors (CXCR1/2, CCR4, CCR8) are well-known to deeply participate in the tumor development and progression in various cancers, including LUAD." (PMID 36419650, 2022). "We found potential immunotherapy targets, for example, ACP5, MAGEH1, TNFRSF9 and CCR8 for tumor infiltrating Tregs and MT1 for exhausted CD8+ T cells (CD8+ Tex cells)." (PMID 35562760, 2022).
tumor (continued). "TIGIT can also upregulate the expression of the chemokine CCL4 and the chemokine receptor CCR8, which help with Treg migration and retention in tumor tissue." (PMID 35008385, 2022). "As CCR8 is known to direct Tregs to the tumor site, researchers applied CCR8 to redirect engineered T cells to the tumor site, while DNR shielded TGF-β for improved therapeutic efficacy." (PMID 35326556, 2022). "CCR8 is important in the development of GBM because, as previously shown, patients with increased CCR8 expression in the tumor show a worse prognosis." (PMID 35955670, 2022). "In solid tumors, CCR8 expressing cells migrate in response to CCL1 ligand secreted by cancer-associated fibroblasts (CAFs), M2-polarized tumor-associated macrophages and Treg cells." (PMID 35874729, 2022). "CCR8 expression in the tumor core in men was lower than in the peritumoral area (p = 0.0033) and lower in the tumor core compared to the women (p = 0.0077)." (PMID 35955670, 2022). "CCR8 controls the immunosuppressive function of tumor infiltrating Treg cells, and blocking CCR8 depletes Treg cells and improves antitumor immune responses." (PMID 35693763, 2022). "Based on publicly available GEPIA database, CCR8 expression levels in human normal tissue are undetectable or very low, compared with the corresponding tumor tissues." (PMID 35693763, 2022). "As the depletion of Treg cells significantly reduces tumor burden, strategies targeting receptors (CCR4, CD25, CTLA-4, CCR8) preferentially expressed on tumor infiltrating Tregs are currently being evaluated in clinical trials." (PMID 36498469, 2022). "CCR8 expression level in Tregs was highest in tumor tissues and higher than in FOXP3− conventional CD4 T cells (conv CD4 T cells)." (PMID 35354899, 2022). "Tumour cells or infiltrating innate leukocytes release chemokines such as CCL17 and CCL22 to promote the migration of thymic Tregs expressing receptors such as CCR4, CCR5, and CCR8 from the secondary lymphoid tissues to the site of tumour." (PMID 35493450, 2022). "In analogy to human skin T cells, I propose that solid tumors mimic skin by providing CCR8-inducing factors necessary for induction of CCR8 in tumor Treg cells." (PMID 35158783, 2022). "Treatment of tumor bearing mice with the anti-CCR8 antibody was highly specific to tumor infiltrating Tregs, sparing both intratumoral effector T cells and Tregs in non-tumor tissues and ultimately enabling effective and long-lasting antitumor immunity." (PMID 35874810, 2022). "The women had a decreased expression of PITPNM3 receptor in the GBM tumor, while in the men a lower expression of CCR8 was observed." (PMID 35955670, 2022). "In bladder cancer, activation of CCR8 by CCL18 causes the migration and invasion of tumor cells, as well as increased expression of vascular endothelial growth factor (VEGF)-C, which then causes lymphangiogenesis." (PMID 35955670, 2022). "While antibody mediated depletion of CCR8+ Tregs via antibody dependent cell cytotoxicity (ADCC) can ameliorate the tumor burden, blocking CCR8 activity using antibodies that are devoid of ADCC capabilities doesn’t seem to create the same effect." (PMID 36248808, 2022). "Murine tumor models including colorectal adenocarcinoma have been used to evaluate the efficacy of targeting CCR8+ Treg cells in the TME." (PMID 35874729, 2022). "In the model mice, we observed infiltration of CCR8+ Tregs in tumor tissue, and treatment of anti-CCR8 antibody resulted in Treg reduction." (PMID 35354899, 2022). "Interacting with its cognate ligand CCL1, CCR8 induced Treg migration and retention in the tumor microenvironment." (PMID 36313180, 2022). "In mouse and human tumour tissues, CCR8+ Treg cells account for 30% -80% of total tumour-infiltrating Treg cells, while that accounts for less than 10% in other tissues." (PMID 36569832, 2022).
tumor (continued). "Among the 18 Treg-specific overlapping genes, ACP5, MAGEH1, TNFRSF9 and CCR8 were exclusively expressed in tumor-infiltrating Tregs and are potential immunotherapy targets for tumor-infiltrating Tregs." (PMID 35562760, 2022). "In this respect, CCR8 represents a more tumor Treg cell-specific target than CCR4, which is known to be broadly expressed among blood and tissue Treg cells." (PMID 35158783, 2022). "We found potential immunotherapy targets, for example, ACP5 and CCR8 for tumor-infiltrating Tregs and MT1 for CD8+ Tex cells." (PMID 35562760, 2022). "Recent studies identified selective CCR8 expression on tumor-infiltrating Tregs; CCR8+ Tregs have been indicated as a possible new target of cancer immunotherapy." (PMID 35354899, 2022). "It will be interesting to examine alternative combination therapies, such as those combining anti-CCR8 antibodies with tumor vaccines or MDSC-targeted therapies." (PMID 35158783, 2022). "The high frequency of CCR8+ tumor‐infiltrating Tregs played a crucial suppressive function and was correlated with poor prognosis in patients with NSCLC." (PMID 35474948, 2022). "Treatment with anti-CCR8 antibody reduced Tregs in tumor tissue and showed a remarkable anti-tumor effect including complete response." (PMID 35354899, 2022). "The primary mode of action was reported to involve antibody-dependent cellular cytotoxicity (ADCC) leading to the elimination of CCR8-expressing tumor Treg cells." (PMID 35158783, 2022). "Compared to virus-specific Th1 cells, this tumor-specific CD4+ T cell state differentially expressed genes associated with Th2 cells, including Igfbp7, Ccl1, Ccr8, and Il13, and downregulated Th1-associated genes, including Ccl5 and Ly6c2." (PMID 35829695, 2022). "Combination therapies using antibodies specific for both CCR8 and PD-1 led to near complete arrest in tumor progression, indicating that these reagents work in synergy." (PMID 35158783, 2022). "In parallel, CCR8− TAMs secrete CCL1 that will activate CCR8 on nearby TAMs increasing tumor inflammation." (PMID 34572939, 2021). "CCR8 plays a rather unique role in regulating the immune response and is preferentially expressed by activated T helper-type 2 cells and tumour cells, which mediates their recruitment to the lymphatics." (PMID 33484377, 2021). "Hence, selective natural killer (NK) cell-mediated depletion of the CCR8+ ti-Tregs using newly generated anti-CCR8 nanobody-Fc fusions, caused a significant reduction in tumor growth and synergized with anti-PD-1 therapy, resulting in complete tumor remission and immunological memory." (PMID 33589525, 2021). "Treatment of LLC-OVA tumor-bearing mice with Nb-Fc1B (treatment schedule) resulted in the complete depletion of CCR8+ Tregs in the TME, whereas CD4+Foxp3− T cells remained unaffected." (PMID 33589525, 2021). "These epCAM CCR8+ DNR CAR T cells were more efficacious at eliminating tumor and promoting survival in a preclinical model of pancreatic cancer than epCAM CAR T cells." (PMID 34868044, 2021). "High levels of expression of chemokine (C‐C motif) receptor 8 (CCR8) discriminate Treg cells within tumours from those found in systemic lymphoid tissues." (PMID 33838058, 2021). "No increase was observed in the number of CD4+ or CD8+ Tconv cells within tumours of Ccr8−/− animals." (PMID 33838058, 2021). "In breast and CRC, a high tumor infiltration by CCR8+FOXP3+ Tregs correlates with a significantly shorter patient overall survival (OS)." (PMID 33924428, 2021). "Strikingly, while intratumoral Treg abundance based on FOXP3 mRNA expression did not correlate with clinical features, stratifying patients based on the CCR8:FOXP3 ratio in the tumor revealed a strong correlation with poor survival in patients." (PMID 34632244, 2021). "The expression of CCR8 was lower in normal tissues than in tumor tissues; but the survival analysis suggested CCR8 is positively correlated with prognosis (the higher the expression of CCR8, the better the prognosis)." (PMID 34306014, 2021).
tumor (continued). "To test the specificity of this signal and of the antibody used in these experiments, we examined anti‐CCR8 antibody staining on the surface of cells within MC38 tumours implanted in WT and Ccr8−/− animals." (PMID 33838058, 2021). "Overall, these data show that the expression of Ccr8 within the LLC-OVA tumor immune compartment is restricted to a subset of Tregs, but also to populations of dysfunctional CD8+ and CD4+ T cells." (PMID 33589525, 2021). "As said before, the ex vivo blockade of CCR8 in MIBC tumor suspension destabilizes TA-Tregs and favors their production of IL-17A." (PMID 33924428, 2021). "A similar molecule currently developed by BMS (BMS-986340) is able to deplete CCR8+ Tregs in human tumor explants." (PMID 33924428, 2021). "In this study, Eruslanov and coworkers stated that CCR8+ TAMs are able to induce FoxP3 in lymphocytes, thus favoring regulatory T cells (Tregs) in the tumor microenvironment of BCa." (PMID 34572939, 2021). "Consistently, we observed minimal impact of systemic CCR8 ablation on the frequency, phenotype and function of tumour‐infiltrating Treg cells and conventional T (Tconv) function." (PMID 33838058, 2021). "Chemokines were recently implicated in organ-specific metastasis of tumour cells, and human CCL1 is a potent monocyte chemoattractant that binds to and exclusively activates CCR8." (PMID 33484377, 2021). "CCR8 expression was significantly upregulated in the TME of multiple tumor types, always showing a significant (p<0,0001) correlation with FOXP3 expression." (PMID 33589525, 2021). "Recent preclinical studies have further demonstrated that anti-CCR8 antibodies efficiently deplete Treg cells and suppress tumor growth in murine colon cancer and bladder carcinoma models." (PMID 34885241, 2021). "Data from human tumor RNA-seq or scRNA-seq studies have demonstrated a high overexpression of the CCR8 gene on TA-Tregs compared to Tregs from NAT and blood." (PMID 33924428, 2021). "A recent study has suggested that CCR8 function is required for Treg cell‐mediated tumour immunosuppression." (PMID 33838058, 2021). "Compared with CCR8 expressed on all Treg cells, CD177 was found to be expressed highly on a subset of tumor-associated Treg cells through flow cytometry." (PMID 34868991, 2021). "Using this same Treg gating strategy, we next examined the surface expression of eight protein markers (CD30, OX40, 4-1BB, TIGIT, PD-L1, IL-1R2, IL-21R, and CCR8) on tumor-infiltrating Tregs of five CRC patients from our South-East Asian cohort." (PMID 33527196, 2021). "The successful CCR8+ ti-Treg depletion resulted in a slightly reduced LLC-OVA tumor growth in comparison to isotype-treated mice." (PMID 33589525, 2021). "In this context, in murine CRC tumor models, targeting CCR8+ Tregs through either anti-CCL1 neutralizing monoclonal antibody (mAb) or anti-CCR8 mAb drastically reduced the tumor infiltration by Tregs while robustly enhancing the antitumor immune response." (PMID 33924428, 2021). "We confirmed high levels of CCR8 expression on tumour‐infiltrating Treg cells, which was abolished on cells from Ccr8−/− mice." (PMID 33838058, 2021). "In tumor-bearing animals, CCR8+ Tregs were also observed in the thymus, but in addition also in the spleen (approximately 9% of the Tregs) and tumor-draining lymph node (approximately 12% of the Tregs)." (PMID 33589525, 2021). "Recent studies have identified high levels of CCR8 expression as a distinguishing feature of Treg cells within tumours." (PMID 33838058, 2021). "Intraperitoneal administration of 200 μg of Nb-Fc1A was done at days 4 and 11 of LLC-OVA tumor growth, resulting in an efficient occupation of CCR8 inside the TME, but also in the spleen, as illustrated by the prevention of subsequent anti-CCR8 mAb binding." (PMID 33589525, 2021). "We found that CCR8 expression was dispensable both for Treg cell accumulation within tumours and for their immunosuppressive function." (PMID 33838058, 2021).